TNF (tumor necrosis factor)
Diseases named in the same sentence as TNF in open-access papers (continued):
Sharing a sentence is not in itself a finding about the gene and the disease.
cryptosporidiosis (7 papers, 2020 to 2025). Intestinal infection with organisms of the genus Cryptosporidium. "Robinson and his co-workers assumed that TNF-α increased in cryptosporidiosis pathogenesis as it was linked with Lamnia propria histological inflammation in porcine cryptosporidiosis." (PMID 40029925, 2025). "The role of TNFα in Cryptosporidium infections is unclear as parasite infectivity in TNFα-deficient mice is unchanged, while exogenous TNFα promotes oocyst shedding." (PMID 37375100, 2023). "At the same time, TNF-α has been found as the central mediator of inflammation to induce the secretion of IL-6, IL-1 and other inflammatory factors, causing the inflammatory response after Cryptosporidium infection in mice." (PMID 38914662, 2024). "This reaffirms that the TNF signaling pathway is particularly important in treating cryptosporidiosis with oxymatrine." (PMID 38914662, 2024). "Based on the establishment of a mouse model of cryptosporidiosis, the validity of the targets in the TNF/NF-κB signaling pathway was confirmed using Western blot analysis and Quantitative Rea-ltime-PCR." (PMID 38914662, 2024). "Cryptosporidium infection in neonatal mice increases the release of TNF-α from inflammatory monocytes, leading to a rapid and significant increase in FITC-Dextran permeability." (PMID 38914662, 2024). "Therefore, it can be concluded that oxymatrine can regulate the inflammatory factors TNF-α, NF-κB, and IL-6 through the TNF/NF-κB signaling pathway for the treatment of cryptosporidiosis." (PMID 38914662, 2024). "However, the expression of TNF-α, NF-κB and IL-6 was reversed after treated with oxymatrine, suggesting that oxymatrine can achieve the therapeutic effect of cryptosporidiosis through the TNF/NF-κB signaling pathway." (PMID 38914662, 2024). "In this study, based on the results of network pharmacology, we established a mouse model of cryptosporidiosis, validated the TNF/NF-κB signaling pathway, and revealed the inflammatory response of cryptosporidiosis on the host and the anti-inflammatory effect of oxymatrine." (PMID 38914662, 2024). "In vivo experiments preliminarily verified that oxymatrine can control intestinal inflammation by regulating the TNF/NF-κB signaling pathway and down-regulating the expression of TNF-α, NF-κB, and IL-6, thereby contributing to the treatment of cryptosporidiosis." (PMID 38914662, 2024). "Therefore, we decided to examine the possible mechanism of oxymatrine therapy for cryptosporidiosis by identifying the TNF/NF-κB signaling pathway." (PMID 38914662, 2024). "Particularly, the TNF signaling pathway is highly ranked and may play an important role in treating cryptosporidiosis with oxymatrine." (PMID 38914662, 2024). "Moreover, IFN-γ along with TNF-α contributes to macrophages releasing higher levels of IL-12 in the initial and early stages of Cryptosporidium infection to control parasite replication." (PMID 35095858, 2021). "In accordance with previous data, the immune response during Cryptosporidium infection presented by an increasing expression of immune mediators such as TNF-α, IL-6, IFN-γ by T-helper cell (Th1) particularly protect against intracellular infections including C. parvum." (PMID 33076496, 2020). "Furthermore, TNF-α together with IFN-γ helps to activate macrophages to release huge amounts of IL-12 to control parasite replication during early Cryptosporidium infection." (PMID 33076496, 2020). "In order to investigate the mechanism of oxymatrine in treating cryptosporidiosis, we constructed a target-KEGG network and identified the top 5 involved genes, namely RELA, AKT1, TNF, CASP3, and IL-6." (PMID 38914662, 2024). "First, we performed a target database search to obtain a total of 47 intersecting targets of oxymatrine for the treatment of cryptosporidiosis, including the core targets of ALB, IL-6, TNF, AKT1, CASP3, and SRC." (PMID 38914662, 2024).
cryptosporidiosis (continued). "SMC administration also reduced cytokines production (SAP, TNF-α, IL-6, and IFN-γ) mediated by Cryptosporidium infection in contrast to the infected untreated group." (PMID 33076496, 2020).
Cushing syndrome (7 papers, 2016 to 2026). Cushing's syndrome (CS) encompasses a group of hormonal disorders caused by prolonged and high exposure levels to glucocorticoids that can be of either endogenous (adrenal cortex production) or exogenous (iatrogenic) origin. "Patients with active or treated Cushing syndrome exhibit elevated inflammatory markers, including C-reactive protein (CRP), interleukin-6 (IL-6), and tumor necrosis factor-alpha (TNF-α)." (PMID 40729034, 2025).
cutaneous lupus erythematosus (7 papers, 2012 to 2024). An autoimmune disorder that manifests as different lupus-specific skin disorders; it can occur with systemic lupus erythematosus, or as a singular disease. "Monocytes and mDCs are present in lesional skin, and the increased TNFα production by these cells and other PBMCs likely increase the number of inflammatory cells seen in DLE skin relative to other subsets of cutaneous lupus erythematosus and DM." (PMID 22217359, 2012). "Several pro-inflammatory cytokines, such as TNF, IL-12, and IL-6, show increased levels in skin lesions of patients with cutaneous lupus erythematosus (CLE) compared to non-lesional skin or skin of healthy individuals." (PMID 39618670, 2024).
cystic kidneys (7 papers, 2015 to 2026). "In keeping with these observations, control-ASO treated cystic kidneys showed elevated levels of the TNF-α and cleaved caspase-1; both were significantly reduced in mice treated with Glis2-ASO." (PMID 38693102, 2024). "Further, TNF-α, an inflammatory cytokine, is present in renal cyst fluid of human ADPKD and induces renal cyst formation through regulating polycystin-2." (PMID 27891514, 2016). "TNFα increases progressively with age in cystic kidneys of the rodent ARPKD model, cpk mice, and consistently presents in the cystic fluid from human ADPKD kidneys." (PMID 26110849, 2015). "We discovered that FTY720 may prevent the activation of inflammatory pathways like STAT3 and NF-kB, decrease the production of pro-inflammatory cytokines like IL-6 and TNF-α, and inhibit the formation of renal cysts in PKD rats." (PMID 41431718, 2026). "Cytokines, such as TNF-α, IL-6, and MCP-1, play crucial roles in renal inflammation within cystic kidneys, which can regulate the recruitment of macrophages in Pkd1 mutant kidneys." (PMID 39456148, 2024). "We found that FTY720 can inhibit the expression of pro-inflammatory cytokines, such as IL-6 and tumor necrosis factor-α(TNF-α), block the activation of inflammatory pathways, such as STAT and NF-κB, and thus inhibit the growth of renal cysts in PKD rats." (PMID 37675342, 2023). "In addition, we found that treatment with cystic cell exosomes increased the expression of TNF-α, IL-6, and MCP-1 in recipient cells and in cystic kidneys." (PMID 34315885, 2021). "Thus, cystic renal epithelial cell secreted EVs/exosomes may be via the upregulation of TNF-α and MCP-1 to increase the recruitment and/or the proliferation of macrophages in cystic kidneys." (PMID 34315885, 2021).
diabetic encephalopathy (7 papers, 2014 to 2025). A brain disease that is characterized by functional impairment of cognition, cerebral signal conduction, neurotransmission and synaptic plasticity, and underlying structural pathology associated with diabetes. "Moreover, as suggested by low expressions of TNF-α, iba1, Fas, and caspase 3 in brain tissue, treatment with F5 also prevented neuroinflammation and neuronal loss, which are key mechanistic features of diabetic encephalopathy." (PMID 35356236, 2022). "Diabetic encephalopathy was characterized by robust neuroinflammatory activation, with pro-inflammatory cytokines significantly elevated: TNF-α (4.7-fold), IL-6 (3.8-fold), IL-1β (3.2-fold), and IFN-γ (2.9-fold) compared to controls." (PMID 40723442, 2025). "The combined effect of the coagulation cascade protein thrombin and the inflammatory factor TNF-α further damages the endothelial barrier function, supporting a coagulation–inflammation interplay in the pathogenesis of diabetic encephalopathy." (PMID 36768341, 2023). "A significant inhibition of TNF-α levels by saffron observed in our study is indicative of the fact that saffron contributes to beneficial effects seen in diabetic encephalopathy." (PMID 25114929, 2014). "Pinocembrin could suppress NF-κB and down-regulate TNF-α expression in a mouse model of diabetic encephalopathy (DE)." (PMID 38419887, 2024). "PARIN5 treatment normalized levels of serum NfL and TNF-α and FX expression, supporting a thrombin-PAR1-related mechanism in diabetic encephalopathy." (PMID 36768341, 2023). "In the present study, significant elevated TNF-α and FX expression levels were measured in the diabetic mice brain, and both were modulated by PARIN5 supporting CNS inflammation and coagulation interplay in diabetic encephalopathy." (PMID 36768341, 2023).
diverticulosis (7 papers, 2014 to 2026). "An association between diverticular disease and elevated TNF‐α has been shown, implying that TNF‐α–mediated mechanisms contributed to the pathophysiology observed in this patient." (PMID 40909304, 2025). "Additionally, several studies have reported elevated colonic mucosal TNF-α levels in symptomatic diverticulosis, including acute uncomplicated diverticulitis and SUDD, while also being associated with disease severity." (PMID 37373082, 2023). "Surprisingly, TNF-α was not positively associated with the presence (p = 0.3) of diverticulosis in our study." (PMID 24740401, 2014). "However, our subjects were asymptomatic and undergoing preventive screening colonoscopy, so the severity of diverticular disease and the TNF-α concentrations among the participants were lower than those reported in the Tursi studies." (PMID 24740401, 2014). "However, the TNF-α levels were found to be significantly increased in DD compared to irritable bowel disease (IBS) patients (27.368 (95% CI 23.744–30.992)), and segmental colitis associated with diverticulosis (SCAD) vs. IBS patients (25.303 (95% CI 19.823–30.784))." (PMID 37373082, 2023). "We did not observe statistical significance related to the mucosal TNF-α levels in symptomatic uncomplicated diverticular disease (SUDD) vs. the controls (0.517 (95% CI −1.148–2.182)), and symptomatic vs. asymptomatic DD patients (0.657 (95% CI −0.883–2.196))." (PMID 37373082, 2023). "Assessing its mucosal expression on biopsy samples by reverse transcription polymerase chain reaction, we found that TNFα expression was significantly higher not only in AUD than in HC (p = 0.0007) but also in SUDD than in HC (p = 0.0007) and in asymptomatic diverticulosis (p = 0.0001)." (PMID 31001067, 2019).
Dupuytren’s disease (7 papers, 2018 to 2025). "Since anti-TNF has shown promise in early stage Dupuytren’s disease, we tested the effect of anti-TNF treatment on collagen synthesis during formation of constructs derived from Dupuytren’s cells." (PMID 40337865, 2025). "In contrast, in normal fibroblasts from the palm of patients with Dupuytren’s disease (DD), a localized fibrotic condition of the hand, TNF treatment drove their conversion to myofibroblasts via activation of Wnt signaling." (PMID 37465675, 2023). "In Dupuytren’s disease, tumor necrosis factor α (TNFα) stimulates myofibroblasts to secrete IL-33, which in turn increase the secretion of TNFα from other immune cells, and finally forms a vicious circle." (PMID 35967331, 2022). "Previously, we identified macrophages and mast cells as the predominant source of TNF within Dupuytren’s nodule cultures and demonstrated that macrophage-derived TNF plays a key role in promoting the fibrotic phenotype in Dupuytren’s disease." (PMID 32759223, 2020). "Here, we present a summary of a health economics analysis plan being undertaken to the second part of the Repurposing anti-TNF for treating Dupuytren’s disease (RIDD) trial, which targets patients with early stage DD." (PMID 30756094, 2018). "While TNF has been identified as a potential therapeutic target in Dupuytren’s disease, information on the response of Dupuytren’s cells and tissues to TNF-α in terms of collagen protein synthesis and production of normal versus abnormal type I collagen is currently lacking." (PMID 40337865, 2025). "The objective of this paper is to describe the methods applied to assess the cost-effectiveness of adalimumab injections compared to usual care for controlling the progression of early stage DD in the Repurposing Anti-TNF for Treating Dupuytren’s Disease (RIDD) trial." (PMID 30756094, 2018). "Hence, modulation of the TNF-α pathway in Dupuytren’s disease is unlikely to prevent the pathological collagen accumulation that is characteristic of fibrosis." (PMID 40337865, 2025). "Hence, it is possible that the beneficial effects of the anti-TNF adulimumab in Dupuytren’s disease could be Fc mediated and not related to modulation of collagen synthesis." (PMID 40337865, 2025).
empyema (7 papers, 2007 to 2024). An accumulation of pus in a body cavity, usually the pleural space. "Previous reports showed the TNF-α levels in empyema and complicated parapneumonic effusions compared to malignant effusions, whereas tuberculous pleural fluid showed the highest TNF-α level." (PMID 27034588, 2016). "Interestingly, baseline levels of TNF-α, IL-6, and IL-8 were in the ranges previously observed for rabbit models of chemically induced pleural injury and advanced 7 d empyema." (PMID 39201465, 2024). "IL-8 has been shown to be produced in rabbit pleural space and by mesothelial cells in vitro but also in the pleural fluid of patients with empyema where its levels is being correlated to the pleural neutrophil count and the levels of tumor necrosis factor-alpha (TNFa)." (PMID 35326567, 2022). "Notably, while levels of PAI‐1, TGF‐β, TNF‐α, IL‐6, and IL‐8 were elevated in both models, they were higher (p < 0.05) in empyema." (PMID 33991465, 2021). "Moreover, levels of PAI-1, TGF-β, TNF-α, IL-6, IL-8 observed in pleural fluids of human patients with empyema and with parapneumonic effusions were also higher than those in the transudative pleural fluids and were comparable to the levels observed in the rabbit empyema model (Table A1)." (PMID 37242740, 2023).
extrapulmonary tuberculosis (7 papers, 2005 to 2025). A tuberculosis that occurs at body sites other than the lung. "Mycobacterium-induced CCL2 and TNFα, and LPS-induced TNFα responses were greater in pulmonary as compared with extra-pulmonary tuberculosis." (PMID 16001981, 2005). "Reduced CCL2 concomitant with lowered TNFα in extra-pulmonary tuberculosis may lead to lowered protective cellular responses and increased dissemination in these patients." (PMID 16001981, 2005).
functional dyspepsia (7 papers, 2009 to 2022). "High-purity astaxanthin has been reported to exert strong anti-inflammatory effects in patients with functional dyspepsia, because it specifically suppresses NO generation, which is connected to TNF-α secretion." (PMID 36185650, 2022). "Indeed, plasma cytokine IL-1β, IL-10, and TNF-α levels are correlated with symptom intensity of pain, cramps, nausea, and vomiting, and associated with delayed gastric emptying, in H. pylori negative functional dyspepsia patients." (PMID 35527812, 2022). "In the present study, it is shown that BHM may play a critical role in treating functional dyspepsia via regulating IL1B, TNF, TRPV1, SERT, and NOS3 signaling pathways." (PMID 35668782, 2022). "In H. pylori negative functional dyspepsia patients, plasma cytokines IL-1β, IL-10, and TNF-α levels are increased compared to healthy subjects." (PMID 35527812, 2022). "We further revealed that JGT might target variety digestion signalings to exert its dyspepsia-relieving activity, which involve Apoptosis, MAPK, TNF, PI3K-Akt, Toll-like receptor signaling pathway and NOD-like receptor." (PMID 36438925, 2022). "In H. pylori negative functional dyspepsia patients, peripheral blood mononuclear cell mediated release of cytokines IL-1β, IL-10, IL-6, and TNF-α were correlated with intensity of pain and cramps, and also nausea, vomiting and delayed gastric emptying, which can lead to reduced food intake." (PMID 35527812, 2022). "Furthermore, duodenal transcript expression of IL-1β, but not TNF-α is increased in functional dyspepsia." (PMID 35527812, 2022).
Genital ulcers (7 papers, 2008 to 2025). "Second, the publication of updated EULAR recommendations and the results of RCTs demonstrating the benefit of TNF inhibitors for oral and genital ulcers strengthened clinicians’ confidence in using these drugs earlier in the disease course." (PMID 41438745, 2025). "Anti-TNF treatment was started at the age of 13 for the appearance of recurrent genital ulcers, with a complete response." (PMID 36159847, 2022).
Helicobacter infection (7 papers, 2012 to 2022). "Upon Helicobacter infection, gastric epithelial cells produce inflammatory cytokines, such as IL-8, and inflammatory cells recruited from the bone marrow accelerate the inflammatory reaction by producing TNF-α or IL-1β." (PMID 29212456, 2017). "The regulation of IL-32 expression in response to H. pylori-infection could be weakened by using neutralizing antibodies to block IL-1β and TNF-α." (PMID 24633341, 2014). "The analysis of the most prominent pro-inflammatory cytokines involved in Helicobacter infection (IL8, IL6, TNFα, IL1β and IFNγ) revealed that the main difference between the two conditioned media was on IFNγ, not expressed in the THP1 system." (PMID 36514982, 2022).
hemophilia A (7 papers, 2019 to 2021). The most common form of hemophilia characterized by spontaneous or prolonged hemorrhages due to factor VIII deficiency. "The role of TNF-α in the pathogenesis of hemophilia arthropathy has been studied in hemophilia A mouse model." (PMID 31892201, 2019). "Serum TNF-α level might be used to differentiate between high and low inhibitor levels in severe hemophilia A, and this might support decision making regarding treatment options for inhibitor in severe hemophilia A." (PMID 34778454, 2021). "The hmrSCs response to BMP9 was enhanced by both Hema and HH, even though several cytokines were upregulated (IL-6, IL-8, MCP-1, VEGF-A and osteopontin), downregulated (BMP9, PDGF) or similar (TNF-alpha) in Hema compared with HH." (PMID 32325892, 2020). "However, the clinical evidence that HA may often affect multiple joints in the same patient and our current observation that circulating TNF-α is strongly increased and correlated with HA severity in hemophilia A patients might, instead, be in favor of a systemic anti-TNF-α therapeutic approach." (PMID 31261789, 2019). "Here, we were interested in determining whether systemic levels of TNF-α and synovial tissue expression of the TNF-α/TNF receptor (TNF-R) system could be increased and related to joint damage in hemophilia A patients with severe HA." (PMID 31261789, 2019). "To investigate whether the TNF-α/TNF-R pathway could contribute to the pathogenesis of human HA, here we combined ex vivo studies on serum samples and synovial biopsies and in vitro studies on isolated fibroblast-like synoviocytes from hemophilia A patients with severe HA." (PMID 31261789, 2019).